LINC01843 (long independently transcribed non-coding RNA 1843)
Synonyms: Lnc-APUE
Gene: Long non-coding RNA gene on chromosome 5 (134,506,422 to 134,509,238, forward strand). Ensembl gene ENSG00000251169.
Diseases named in the same sentence as LINC01843 in open-access papers:
LINC01843 is named in the same sentence as 1 disease in open-access papers, as found by Europe PMC text mining. Sharing a sentence is not in itself a finding about the gene and the disease. The quoted sentences say what the papers report.
tumor (1 paper, 2025). "LINC01843 was predominantly expressed in tumor epithelial cells, indicating a possible role in tumor-intrinsic biological functions." (PMID 40909272, 2025).